DYRK1B (dual specificity tyrosine phosphorylation regulated kinase 1B)
Diseases named in the same sentence as DYRK1B in open-access papers (continued):
Sharing a sentence is not in itself a finding about the gene and the disease.
steatosis (1 paper, 2022). Increased lipid within the cytoplasm of cells. "Since patients with T2D and NASH exhibit increased DNL, we investigated whether Dyrk1b-induced steatosis is due to increased hepatic DNL." (PMID 34855620, 2022). "Altogether, these data indicate that Dyrk1b causes steatosis directly in the hepatocytes irrespective of its kinase activity." (PMID 34855620, 2022).
cancer (41 papers, 2010 to 2026). A tumor composed of atypical neoplastic, often pleomorphic cells that invade other tissues. "DYRK1B kinase represents a significant pharmacological target in cancer therapy due to its frequent overexpression in various tumors, whereby elevated DYRK1B levels are associated with poor clinical outcomes and reduced survival rates in patients." (PMID 40002350, 2025). "In correlation with the predicted cancer pathways, DYRK1B was also found to have a functional association with RNF169, which predicts its role in DNA damage." (PMID 35454940, 2022). "Expression and activation of serine/threonine-protein kinase dual-specificity tyrosine-(Y)-phosphorylation regulated kinase 1B (DYRK1B) is associated with growth and survival of many types of cancer cells." (PMID 29568347, 2018). "Systematic sequencing of cancer genomes has revealed rare mutations in DYRK1B including L28P, R102H, S234G and Q275R." (PMID 26346493, 2016). "The results support the use of DYRK1B antagonists for the treatment of HH/GLI-associated cancers where SMO inhibitors fail to demonstrate therapeutic efficacy." (PMID 26784250, 2016). "The serine/threonine kinase Mirk/dyrk1B is a downstream effector of oncogenic K-ras, the most common mutation in this cancer." (PMID 24281169, 2010). "Moreover, DYRK1B has been associated with the repair of DNA damage, of which DNA double-strand breaks (DSBs) pose a particular threat to cancer cells." (PMID 39863750, 2025). "Eventually, the overall ability of DYRK1B to slow proliferation as well as to foster survival might be one reason why this kinase has previously been linked to cancer stem cells and stem cell-enriched tumor spheroids." (PMID 39863750, 2025). "During development Dyrk1B has a critical role in myogenesis, spermatogenesis and adipogenesis, while it is implicated in human diseases, such as metabolic syndrome, and tumor progression promoting survival and chemoresistance in cancer cells." (PMID 38294527, 2024). "Dyrk1B plays a critical role in myogenesis, spermatogenesis, adipogenesis, and neurogenesis, and it is implicated in human diseases, such as metabolic syndrome and cancer." (PMID 38675189, 2024). "Of note, DYRK1B has previously been implicated in the regulation of cancer cell migration." (PMID 39482615, 2024). "In addition, cancer genome sequencing has revealed mutations in DYRK1B including L28P, R102H, S234G and Q275R." (PMID 26346493, 2016). "In addition, DYRK1B is amplified and mutated in certain cancers and has been reported to promote cell survival." (PMID 26346493, 2016). "Dyrk1B may serve as a target for therapy in HPV-associated cancers." (PMID 26307683, 2015). "The protein kinase DYRK1B, known to promote cancer cell survival and contribute to DNA damage repair, is overexpressed in various tumor types." (PMID 41888523, 2026). "DYRK1A and DYRK1B play key roles in neurodevelopment and cancer biology and are increasingly recognized as potential drug targets in disorders including Alzheimer’s disease, diabetes mellitus, metabolic syndrome, heart disease, and cancer." (PMID 41444824, 2025). "In this review, we will focus particularly on the role of DYRK1B as it comprises the family member most studied for its role in cancer." (PMID 39863750, 2025). "For example, the gene DYRK1B is highly expressed in many cancer types where it is involved in arrest of the cell cycle but is also involved in resistance to chemotherapy." (PMID 40391157, 2025). "Pharmacological modulation of DYRK1B thus represents a very promising anti-cancer strategy, acting on multiple layers to control macrophage immunity." (PMID 39863750, 2025). "While thus far most of the functions attributed to DYRK1B are intrinsic to tumor cells, the interaction between cancer cells, stromal as well as immune cells significantly influences tumor progression and response to therapy." (PMID 39863750, 2025).
cancer (continued). "In summary, DYRK1B appears as a single novel key player creating a safe haven for cancer cells by acting cell-intrinsically and—extrinsically, leading to the promotion of cancer cell survival, chemoresistance, and relapse." (PMID 39863750, 2025). "Here we proposed DYRK1B as an attractive therapeutic target as it promotes cancer growth by simultaneously modulating cell-intrinsic as well as TME aspects, functionally creating a protective niche for malignant cells." (PMID 39863750, 2025). "Here, recent evidence suggests that DYRK1B exerts its oncogenic features by installing a protective niche for cancer cells by directly affecting cancer cells but also the TME." (PMID 39863750, 2025). "In this study, we employed A549 and PANC-1 cancer cell lines to explore the expression of DYRK1B and DYRK1A in response to serum deprivation and increased cell density." (PMID 39397076, 2024). "Our present study has identified various conditions under which DYRK1B is upregulated in cultivated cancer cells." (PMID 39397076, 2024). "DYRK1B appears to play a more important role in cancer cell quiescence than DYRK1A, as evidenced by its overexpression or copy number variations in human tumour samples." (PMID 39397076, 2024). "Nevertheless, the function of DYRK1B in cancer cells is insufficiently understood, and it is classified as a “dark kinase” in the Dark Kinase Knowledgebase." (PMID 39482615, 2024). "Taken together, the present study demonstrates that high expression levels of DYRK1B not only halt proliferation of A549 cells but induce alterations in cell morphology, behavior and gene expression that are characteristic for cancer cell EMT." (PMID 39482615, 2024). "Pharmacological inhibition of DYRK1B has garnered attention as a potential therapeutic principle to counteract chemo- and radioresistance in cancer therapy." (PMID 39482615, 2024). "Numerous studies have reported that Dyrk1A, Dyrk1B, and Clk1 are overexpressed in multiple cancers, suggesting a role in malignant disease." (PMID 38893153, 2024). "For instance, genetic mutations, particularly in the Wnt/β-catenin pathway and DYRK1B gene, play roles in both CVD and cancer." (PMID 39340596, 2024). "While DYRK1B is recognized to promote cell survival and adaption to stressful conditions, the consequences of elevated DYRK1B levels in cancer cells are largely uncharted." (PMID 39482615, 2024). "Future investigations of stemness traits in DYRK1B overexpressing A549 cells and in other cell models will be necessary to answer the question how DYRK1B affects the self-renewal properties of cancer cells." (PMID 39482615, 2024). "Most of the Dyrk1B inhibitors reported to date are proven effective in cancer treatment, but still exhibit off-target effects on other GMGC or DYRK kinases, and mainly on Dyrk1A, the closest member of Dyrk1B." (PMID 38675189, 2024). "Short term effects of increased DYRK1B expression levels on cell cycle exit and cancer cell chemoresistance have been characterized in several cancer cell lines." (PMID 39482615, 2024). "Similar to the Dyrk1A homologue, Dyrk1B was shown to induce cancer cells into a dormant state, thus rendering the cells resistant to chemotherapy." (PMID 38893153, 2024). "As Dyrk1B has been previously shown to have an anti-apoptotic role in myogenesis and cancer, we investigated if it has a similar function in the developing chick SC." (PMID 38294527, 2024). "In this review, apart from summarizing the data establishing Dyrk1B as a therapeutic target in cancer, we highlight the most potent Mirk/Dyrk1B inhibitors recently reported." (PMID 38675189, 2024). "As Dyrk1B has been established as a pharmacological target in cancer therapy, the discovery of Dyrk1B-specific and potent inhibitors has become even more desired and highly needed." (PMID 38675189, 2024). "Recently, Dyrk1A and Dyrk1B have been evaluated as therapeutic targets for neurodegenerative diseases and cancer, respectively." (PMID 38675189, 2024).
cancer (continued). "Many studies have demonstrated the valuable therapeutic effect of Mirk/Dyrk1B inhibitors in cancer cell lines, mouse xenografts, and patient-derived 3D-organoids, providing a perspective for entering clinical trials." (PMID 38675189, 2024). "Given that cancer cells require active Dyrk1B kinase to remain in a G0 quiescent state, the pharmacological inhibition of Dyrk1B is a possible therapeutic strategy to overcome the chemo- and radio- resistance of quiescent cancer cells." (PMID 38675189, 2024). "The survival kinase DYRK1B (dual-specificity tyrosine phosphorylation-regulated kinase 1B) has been shown to be upregulated in dormant cancer cells, promoting dormancy by stabilizing the CDK inhibitor and inducing the degradation of cyclin D." (PMID 39682769, 2024). "DYRK1B mutations are associated with CVD risk factors such as obesity, CAD, hypertension, and diabetes and regulate cellular survival in cancer." (PMID 39340596, 2024). "In contrast, in vitro studies and analysis of clinical samples point mostly to a pro-tumorigenic role of DYRK1B and establish DYRK1B as a potential drug target in cancer therapy." (PMID 39482615, 2024). "In the present study, we established an inducible overexpression system to characterize the effects of increased DYRK1B levels in A549 cells as a cancer cell model." (PMID 39482615, 2024). "Pharmacological inhibition of Dyrk1B leads quiescent cancer cells to re-enter the cell cycle, rendering them vulnerable to conventional cancer treatments, induces apoptosis in cancer cells, and reduces tumor size in vitro and in vivo." (PMID 38675189, 2024). "Overall, the phenotypic effects of DYRK1B overexpression are similar to the alterations that are typically observed in carcinoma cells undergoing epithelial-to-mesenchymal transition (EMT)." (PMID 39482615, 2024). "On the contrary, decreasing the level of DYRK1B by RNA interference enables C2C12 myoblasts to re-enter the cell cycle, suggesting that DYRK1B plays an important role in maintaining cancer cells in a quiescent state." (PMID 36835173, 2023). "Substantial evidence indicates that the depletion or inhibition of DYRK1B drives cell cycle re-entry and enhances the apoptosis of those quiescent cancer cells with high expression of DYRK1B." (PMID 36835173, 2023). "Dyrk1b is an arginine-directed serine/threonine protein kinase which is highly expressed in many cancers." (PMID 35630356, 2022). "Accordingly, treatment with DYRK1B inhibitors forces cancer cells to enter the cell cycle and makes them drug-sensitive." (PMID 35326533, 2022). "DYRK1B prevents cancer cells from staying in G0 stage of the cell cycle, which is the most chemotherapy-resistant stage." (PMID 35326533, 2022). "Based on these findings, small molecule inhibition of DYRK1B was proposed to be a promising approach to target GLI1-dependent cancers resistant to SMO inhibitors." (PMID 35163655, 2022). "Targeting DYRK1B is also suggested as a novel alternative strategy to overcome the drug resistance in GLI1-dependent cancer." (PMID 35163655, 2022). "The protein kinase dual-specificity tyrosine-Y-phosphorylation regulated kinase 1B (DYRK1B) plays a key role in the G0/G1–S phase transition, which is necessary to maintain cancer cells in a quiescent state." (PMID 34490236, 2021). "The dual‐specificity tyrosine‐regulated kinases DYRK1A and DYRK1B play a key role in controlling the quiescence‐proliferation switch in cancer cells." (PMID 34708541, 2021). "Regarding the mechanisms of DYRK1B on cancer progression, silencing DYRK1B consistently reduced two rare genes, CCDC97 and ZNF581, the physiological functions of which have not been previously reported." (PMID 34830933, 2021). "The involvement of DYRK1B in cancer malignancy was evaluated with migration, invasion assays, and spheroid culture." (PMID 34830933, 2021).
cancer (continued). "Compounds targeting DYRK1B, with either restricted or broad specificity, have been used as research tools, and they display toxicity towards several types of cancer cells or they promote the cell cycle re-entry of quiescent tumor cells." (PMID 32751160, 2020). "The first studies into the influence of DYRK1B in cancer suggested a role in the survival of cancer cells, with a stronger DYRK1B expression in CRC samples than in normal tissue." (PMID 32751160, 2020). "Eight understudied kinases were found to have hotspot mutations in at least one cancer (CDC42BPA, DYRK1B, DYRK4, LMTK3, MAPK15, NEK7, TSSK1B, and TTBK1), with DYRK4, LMTK3, MAPK15, and NEK7 all having significant hotspot mutations in STAD." (PMID 33205077, 2020). "We propose that small molecule inhibition of DYRK1B represents a novel and promising approach to target HH/GLI-associated cancers including malignancies with acquired or de novo resistance to SMO inhibitors." (PMID 26784250, 2016). "Together, these data identify DYRK1B as possible therapeutic target to overcome SMO-inhibitor resistance in GLI1-dependent cancer cells." (PMID 26784250, 2016). "Genetic and chemical inhibition of DYRK1B in human and mouse cancer cells resulted in marked repression of HH signaling and GLI1 expression, respectively." (PMID 26784250, 2016). "This study was performed to investigate the effect of Mirk/Dyrk1B on cell cycle and survival of human cancer cells involving MAPK/ERK signaling." (PMID 23311607, 2013). "As part of a phosphoproteomics screen in human cancer cells, we identified peptides corresponding to the pY autophosphorylation site of Mirk/Dyrk1B in NSCLC cells." (PMID 23311607, 2013). "Taken together, the widely expressed Mirk/Dyrk1B in the human cancer cells is positively correlated with the levels of activated ERK1/2." (PMID 23311607, 2013). "Recently, studies have focused on the effect of Mirk/Dyrk1B on various human cancer cells arrested in a reversible quiescent state (G0-G1) to undergo DNA repair or survive suboptimal growth conditions." (PMID 23311607, 2013). "Our study demonstrated the widely expressed Mirk/Dyrk1B proteins in the human cancer cells were positively correlated with the levels of activated ERK1/2." (PMID 23311607, 2013). "More recently, the serine/threonine kinase Mirk/Dyrk1B has been thought to be a transcriptional co-activator which increases expression of a cohort of antioxidants in human cancer cells." (PMID 22159921, 2012). "ROS arise during normal biological processes such as oxidative phosphorylation in mitochondria, but increased ROS levels may lead to DNA damage and cell death and high DYRK1B levels might thus protect cancer cells." (PMID 39863750, 2025). "Notably, DYRK1B is found to be overexpressed in certain cancers, and inhibitors targeting DYRK1B have shown promising therapeutic effects in cancer treatment." (PMID 40799825, 2025). "In a recent study by us, we could demonstrate that inhibitors of DYRK1B provide a novel and clinically translatable approach to targeting both the cancer cell compartment and its microenvironment." (PMID 39863750, 2025). "Although these data do not provide a direct link to tumor immunity, they collectively demonstrate that pharmaceutical compounds targeting DYRK1B could potentially intervene not only in the cancer cell compartment but also in its microenvironment." (PMID 39863750, 2025). "Importantly, targeting DYRK1B downregulated the “don’t eat me” signal CD24 on cancer cells, resulting in enhanced tumor cell phagocytosis by macrophages." (PMID 39863750, 2025). "The concept of DYRK1B as a promoter of cancer relapse due to its cell-intrinsic regulation of cell cycle and survival might thus be too narrow." (PMID 39863750, 2025). "In addition, combinatorial treatment of SW872 and SW982 cells with AZ191 and doxorubicin resulted in increased cytotoxicity as detected by MTT assay, suggesting that Dyrk1B inhibition enhances the anti-cancer effects of doxorubicin." (PMID 38675189, 2024).